CD44 (CD44 molecule (IN blood group))
Diseases named in the same sentence as CD44 in open-access papers (continued):
Sharing a sentence is not in itself a finding about the gene and the disease.
cancer (continued). "Indeed, CD44 is an SC marker that has been widely studied for its role in the development of many cancer types." (PMID 37005380, 2023). "Then, a correlation analysis of CD44 and the prognosis of pan-cancer patients were conducted." (PMID 37117249, 2023). "Additionally, the expression levels of both ELF4 and FUT9 were significantly positively correlated with the expressions of the cancer stemness markers CD44 and CD133." (PMID 37674363, 2023). "The CD44, as a key antigen of cancer stem cells (CSCs), is a transmembrane glycoprotein receptor." (PMID 36759786, 2023). "Previous studies showed that CD44 may be a therapeutic target for glycolytic cancer cells that exhibit drug resistance." (PMID 37919747, 2023). "Also, researchers validated CD44 as a potentially functional target of miR34a, where the CD44 knockdown by miR34a over-expression leads to the inhibition of cancer cell regeneration and metastasis." (PMID 37149609, 2023). "MCSs display an increase in both CD44 (cancer stemness) and MMP9 (metastasis) expression." (PMID 37048115, 2023). "ALDH1, CD133, CD44, Lgr5, Msi-1, and EphB1 are markers of cancer stemness." (PMID 36797277, 2023). "Additionally, CD44 serves as a molecular marker for cancer stem cells (CSCs) and is frequently employed alone or in conjunction with other putative CSC markers to isolate CSCs from solid tumors through flow cytometry sorting." (PMID 37509716, 2023). "CD44 expression in cancer has been correlated with both poor and favourable outcomes; however, growing evidence now suggests that overexpression of CD44 and its isoforms is an unfavourable prognostic indicator in cancer patients." (PMID 37958796, 2023). "Thus, CD44 undergoes isoform switching in cancer cells and understanding its regulation mechanisms is incredibly important for a deeper insight into malignant progression." (PMID 38106992, 2023). "Thus, it is imperative to deeply explore the role of CD44 using pan-cancer analysis, thereby providing a novel avenue for developing novel treatments and individualized therapies." (PMID 37117249, 2023). "In addition, HA can specifically bind to CD44 with high binding affinity (Kd ≈ 10−12 M), a cell surface receptor overexpressed on a variety of cancer cells." (PMID 36987181, 2023). "A randomized phase II trial of HA-irinotecan on CD44-expressing SCLC showed significant clinical benefit in patients, suggesting that delivery of chemotherapeutic agents to activated CD44, thereby abrogating the interaction of CD44 with HA, is a compelling approach to cancer treatment." (PMID 37853413, 2023). "Additionally, cancer stem cells expressing CD44+/PrPC+ exhibited a higher liver metastatic capacity compared to CD44+/PrPC- stem cells from CRC, emphasizing the contribution of PrPC to cancer metastasis." (PMID 37894349, 2023). "CD44 is a cell surface glycoprotein used to isolate cancer stem cells in HNSCC." (PMID 36675308, 2023). "One of these molecular prognostic markers could be CD44, which is a compelling marker for cancer stem cells (CSCs) of many solid malignancies, including RCC." (PMID 36831550, 2023). "This indicates that CD44 expression showed lesser positivity in poorly differentiated carcinoma." (PMID 37461792, 2023). "While CD44 is expressed in normal epithelial cells, carcinoma cells overexpress CD44." (PMID 36289579, 2023). "Normal epithelial cells express CD44, while carcinoma epithelial cells overexpress it." (PMID 36289579, 2023). "Thus, in both studies, the numbers of CD44-expressing cells significantly exceeded the burden of TICs, previously identified to be at the level of 0.2–0.8% for carcinoma cells." (PMID 37108193, 2023). "SP+ and CD44+ have recently been reported as potential CSC markers of the majority of cancers." (PMID 35934718, 2022). "CD44 is recognized as a marker for cancer stem cells (CSCs)." (PMID 35931675, 2022).
cancer (continued). "Additionally, CD44 has already been identified in cancer stem cells (CSCs), improving their motility, and in macrophages, making these tumors immunosuppressive." (PMID 36297526, 2022). "Interestingly, in addition to its famous function as a cancer stem cell marker and the regulation in cell adhesion, CD44 has been shown to bind to osteopontin, leading to cancer cell movement, motility, and chemotactic behavior." (PMID 35457063, 2022). "Therefore, limiting the extracellular metastasis of CD44 is a possible pathway of cancer metastasis inhibition." (PMID 34939255, 2022). "In addition, if p38 was inhibited, resistant HNSCC cells showed a higher DNA damage response and exhibited a decreased expression of cancer stem-cell markers such as CD44 and KLF4." (PMID 36289744, 2022). "In addition, CD44 has shown prognostic values and promising therapeutic potential in multiple human cancers." (PMID 35229451, 2022). "The inappropriate regulation of CD44 would participate in formation of numerous cancers." (PMID 36217151, 2022). "Another protein of note is CD44, which is overexpressed on the surface of cancer-initiating cells." (PMID 34995109, 2022). "I found that CD44, another cancer stem cell marker, was upregulated in OVCAR4-PR2 as well." (PMID 36139693, 2022). "Then, we prove the multiplexing technique can be applied to a biosensing application, employing four sensors with two different biofunctionalizations for the simultaneous detection of two cancer biomarkers, namely CD44 and HER2, which are both employed in the diagnostics of breast cancer diseases." (PMID 36421126, 2022). "Hence, we investigated if the amount of P-PKM2 Tyr105 detected in the HNSCC cell lines correlates with the expression of cancer stem cell marker gene CD44." (PMID 35054968, 2022). "In addition, different isoforms of CD44 regulate cancer progression in many ways and have become an important drug target for tumors." (PMID 35504883, 2022). "Therefore, degradation of CD44 through the ubiquitin-proteasome system is a potential therapeutic strategy for the treatment of cancer." (PMID 36605595, 2022). "CD44 is a member of the transmembrane glycoprotein family, and involves in several physiological and pathological processes, including hematopoiesis, inflammation, and cancer." (PMID 35847921, 2022). "SATB2 may be a driving force for developing cancer stem‐like phenotypes in damaged hepatocytes where induction of stem cell markers (CD44, CD90, EpCAM, AFP and LGR5) and pluripotency maintaining factors (POU5F1/Oct4, Sox‐2, Nanog and KLF4) was prominent." (PMID 35152538, 2022). "CD44 is expressed in many tissue cells in humans and is overexpressed in cancers." (PMID 35733341, 2022). "This might be one of the mechanisms driving high invasive potential of those cells however interaction between catulin and CD44 pathway needs further investigating, in terms of cancer propagation." (PMID 35879327, 2022). "Moreover, the expression of different isoforms of CD44 can confer a stem cell profile to tumor cells of many cancers." (PMID 35406498, 2022). "CD44 is a cancer cell marker that is abundantly expressed in many types of cancers." (PMID 35814435, 2022). "Its cell-surface receptor CD44 is a single pass transmembrane glycoprotein expressed by a number of cell types including bone marrow mesenchymal cells, immune cells, embryonic stem cells and cancer stem cells." (PMID 35386200, 2022). "Certain CD44 isoforms, such as CD44v6, are suggested to possess cancer-initiating ability." (PMID 35172821, 2022).
cancer (continued). "We could show that in our patient cohort, a substantial amount (46% ± 15%) of PC cancer cells expressed the stem cell marker CD44 and 5% (± 9%) the stem cell marker CD133." (PMID 35844581, 2022). "Our work found that KDM6B occupies the promoter of CD44 during matrix detachment of cancer cells." (PMID 35186918, 2022). "In addition, many reports have shown that lipid rafts can play an important role in cancer metastasis by regulating a series of signalling pathways related to cell adhesion and migration, such as the CD44 signalling pathway." (PMID 34939255, 2022). "This correlates with the expression of CD44, a well-defined marker for cancer stemness." (PMID 35054968, 2022). "These include ALDH1, ABCG2, CD44, CD133, NANOG, and SRY-box transcription factor 2 (SOX2), all of which have been linked to chemoresistance in a number of first line anti-cancer therapies—for example, axitinib is an oral, potent, small molecule ATP-competitive multitarget tyrosine kinase inhibitor." (PMID 36338714, 2022). "This study materializes the concept of glycoproteogenomics and provides a key vision to address the cancer splicing code at the protein level, which may now be expanded to better understand CD44 functional role in health and disease." (PMID 35547758, 2022). "We constructed a PPI network via a STRING database to study the interaction between CD24, CD44 as cancer stem cell markers, and vimentin and E-cadherin as epithelial mesenchymal transition markers with a significant expression of the proteomics composition of WHF." (PMID 35735628, 2022). "The pleiotropic functions of CD44 in cancer could provide a novel biological target for targeted therapy." (PMID 35845934, 2022). "In addition, the DRM index was found to strongly correlate with the expression of cancer stem cell biomarker CD44 for HNSCC patients." (PMID 35875108, 2022). "CD44 supports signaling that not only inhibits but also promotes cancer progression." (PMID 35547745, 2022). "Furthermore, cancer stemness was decreased in CD44 knocked down ZR75 cells and increased in CD44 overexpressed MCF7 and ZR75 cells." (PMID 36289750, 2022). "Given that Ezrin phosphorylation necessitates the activation of the p38 MAP kinase, we further investigated whether CD44-Ezrin complexes could induce cancer cells dissemination through p38 activation." (PMID 35680853, 2022). "Finally, we tested the in vivo anti-cancer drug delivery ability of CD44-Apt1 for promoting growth inhibition of CD44E or CD44s positive Hep3B xenografts in Nude mice." (PMID 34976591, 2022). "Different CD44 subtypes may be involved in the metastasis and recurrence of different malignant tumors; however, the research on the role of different CD44 subtypes remains incomplete, and further exploration is needed." (PMID 36182897, 2022). "These PSs may also contribute to the differentiation of cancer cells according to the reduction of CD44 protein expression." (PMID 35631686, 2022). "For instance, encouraging pre-clinical studies were presented concerning CAR-Ts targeting Tn and STn antigens in MUC1 97, which may now be adapted for more cancer specific proteoforms such as CD44-Tn/STn." (PMID 35547758, 2022). "Compared with that in monolayer or ALDH-CD44- cancer cells, significantly higher PFKFB3 mRNA expression was clearly detected in tumorspheres derived from ascites and ascites-derived cell lines (SKOV3 and OVCAR3) or ALDH+CD44+ cells sorted from SKOV3 and OVCAR3 cells." (PMID 35155224, 2022). "Hyaluronan can interact with cancer cells via cell surface receptors CD44 and RHAMM." (PMID 35800896, 2022). "Then, exploring the functional implications of CD44 in cancer cells, we demonstrated that this glycoprotein may play a pivotal role driving cell proliferation and invasion." (PMID 35547758, 2022). "CD44 is a cancer stem cell marker and is known to interact with OPN, FN1, and Ezrin 36-38." (PMID 34976221, 2022).
cancer (continued). "Therefore, targeting CD44 and its signaling pathways that involve in the cancer-promoting activities has emerged as a novel therapeutic potential for OSCC." (PMID 35629265, 2022). "PRG4 has been observed to inhibit cancer progression through the CD44/TGF-β pathway." (PMID 35936713, 2022). "The results revealed that basal-type cancer cells had elevated levels of CD44 expression." (PMID 36289750, 2022). "However, the mechanisms of how cancer cells undergo CD44 isoform switching and become resistant to chemotherapy therapy are unclear." (PMID 35931675, 2022). "Notably, HA has been found to bind to the receptor of cluster of differentiation maker-44 (CD44), which is found in abundance on cancer cell membranes, and because tumor selectivity is an important issue for developing cancer treatment agents." (PMID 35159842, 2022). "CD81 and CD44 are required for exosome-induced cancer stemness." (PMID 36193887, 2022). "Moreover, from our previous study, CD44 switching was found to be related to the stemness and plasticity of cancer cells, showing the capability to give rise to collective invasion." (PMID 35680853, 2022). "Interestingly, several CD44-targeted drugs have been approved for clinical trials, which highlights the importance of timing treatment in cancer therapy targeting CD44 (reviewed in98)." (PMID 35552415, 2022). "One of the stem cell markers that is commonly expressed in various cancer types, including GBM is cluster of differentiation 44 (CD44), a surface adhesion receptor which promotes cancer progression and metastasis; its expression in GBM cells is also crucial for GBM invasion and migration." (PMID 35008426, 2022). "Thus, CD44 and CD29 have been determined as cancer-stem cell markers and a high CD44 phenotype in SCC is suggested to identify candidates for implementing targeted therapy." (PMID 35572966, 2022). "In contrast, cancer cells that have high rates of CD44 are more resistant to apoptosis." (PMID 36613567, 2022). "We formulatedand characterized cubosomes loaded with potential cancer drug copperacetylacetonate and functionalized their surfaces using click chemistrycoupling with hyaluronic acid (HA), the ligand for the cell surfacereceptor CD44." (PMID 35938983, 2022). "By using the introduction of a novel CDHA gatekeeper and the specific interaction with the Fc molecule, the MOS-Fc-CDHA nanocomposites protected the drug leakage, controlled the drug release by the enzyme (HAase), and provided the selective internalization to the CD44-overexpressing cancer cells." (PMID 36358509, 2022). "Furthermore, a significant association between high CD44, HAS2 and HAS3 mRNA levels and a cancer-cell pericellular HA-deposition pattern was noted." (PMID 36428513, 2022). "Hence, downregulation of CD44 in cancer cells would inhibit migration and the invasion of cells through the impairment of β-catenin expression." (PMID 36231019, 2022). "Interestingly, NCs reduced the viability of Caco-2 cells and cancer stem cell markers in triple-positive CD133, survivin and CD44 cancer stem-like cells." (PMID 35264972, 2022). "Moreover, ASPN upregulates CD44 expression and activates Rac1 via interaction with CD44 on the cell membrane, which also increases cancer cell spreading." (PMID 34379869, 2022). "Further, we found that mebendazole (MBZ), a benzimidazole derivative, exhibited the most effective anticancer effects in TNBC through inducing DNA damage, cell cycle arrest, and downregulating cancer stem cell markers CD44 and OCT3/4 and cancer progression-related ESM-1 protein expression." (PMID 36555137, 2022). "The expression of CD44 was confirmed in various types of cancers with stemness characteristics, including breast, prostate, colon, and pancreatic cancer, and in head and neck squamous carcinomas." (PMID 35629138, 2022).
cancer (continued). "In this study we show that these factors, although probably not even modulated to a reduced level similar to the in vivo situation, may contribute to a more aggressive cancer phenotype by acquiring a more CD44+/CD24− CSC-like appearance." (PMID 35406578, 2022). "Most metastatic cancer cells in the blood circulation and distant tissues are still closely connected with CAFs, and CD44 may be an important mediator of heteromorphic binding on the basis of scientific researches." (PMID 36059616, 2022). "Thus, CD44-targeted NIR-PIT presents the opportunity to eliminate cancer cells, including cancer stem cells, in particular, thereby reducing the likelihood of recurrence." (PMID 35740662, 2022). "As a result, CD44 can be used as a biomarker to target cancer." (PMID 36613567, 2022). "CD44 has long been known to drive cancer progression and aberrant cell signaling." (PMID 35257663, 2022). "Nanoemulsion modification with HA is justified by its bioadhesive properties (to prolong mammary tissue retention) and its affinity for the differentiation cluster protein 44 (CD44), a receptor overexpressed in several types of cancer, which has been suggested to aid cancer cell targeting." (PMID 36145331, 2022). "CD44 expression inhibits ferroptosis in cancer cells in an OTUB1-dependent manner." (PMID 36612069, 2022). "Furthermore, tumorspheres and the ALDH+CD44+ cell subset originating from ascites had greater expression of PFKFB3 than differentiated cancer cells." (PMID 35155224, 2022). "myCAFs may also express other matrix proteins including THBS1 (thrombospondin 1), THBS2, and TNC (tenascin C, a matrix protein), to communicate with immunocytes, smooth muscle cells, cancer cells, and plasma cells through CD44, integrin (α3β1), and SDC1." (PMID 35986392, 2022). "In vitro studies further verified that the CD24−/CD44+ cancer cell population exhibited a self-renewal capacity and could differentiate into bulk cancer cells." (PMID 36230903, 2022). "The reattached cells also expressed stem cell markers CD133 and CD44, which may play a critical role in cancer cell invasion and metastasis." (PMID 36314970, 2022). "CD44 may also counteract programmed cell death, which leads to tumorigenesis and partly promotes PD-L1 expression to mediate cancer cell proliferation and immune evasion." (PMID 35884507, 2022). "Notably, alcohol dehydrogenase-1 family member A1 (ALDH1A1) is a marker of chemoresistance and cancer stem-like properties in addition to CD44 and CD24." (PMID 35892853, 2022). "Together with the advantages of using HA as a biomaterial, the functional dysregulation of the two main HA receptors, CD44 and RHAMM, has been associated with chronic inflammation and cancer, providing HA-decorated micelles with features diseased cells recognize more effectively." (PMID 36233094, 2022). "Interestingly, a combination of CD29 and CD44 was suggested to identify cancer stem-like cells (CSC) undergoing EMT in SCC." (PMID 35572966, 2022). "CD44 is considered a marker of drug resistance and a surface marker of cancer stem cells." (PMID 35715750, 2022). "CD44 is one of the proteins affected by RNA splicing, largely observed in cancer cells." (PMID 35707369, 2022). "Since CD44 has been connected with cell cycle progression and proliferation of cancer cells of various origins, we analysed the proliferation of CD44 KO cells using a cell counting assay; we observed a significant reduction in cell numbers of KO clones compared to the parental cells." (PMID 35954411, 2022). "HA interacts with various cell surface receptors, including those involved in intracellular signaling pathways, such as the tyrosine kinase pathway and the hyaluronan-mediated motility receptor CD44, to increase proliferation, survival, and resistance to cancer cells." (PMID 35464064, 2022). "CD44 regularizes cancer cell creation and metastatic evolutions." (PMID 35860333, 2022).